MYL9 (myosin light chain 9)
Diseases named in the same sentence as MYL9 in open-access papers (continued):
Sharing a sentence is not in itself a finding about the gene and the disease.
lung adenocarcinoma (5 papers, 2017 to 2025). A carcinoma that arises from the lung and is characterized by the presence of malignant glandular epithelial cells. "Conversely, the dephosphorylation of MYL9 via Y27632 accelerated invasion in noninvasive lung adenocarcinoma cell lines." (PMID 34821071, 2022). "Although treatment protocols that reduce MYL9 phosphorylation are beneficial for reducing the progression of invasion in hepatoma and ovarian cancer, dephosphorylation of myosin regulatory light chain (MYL9) by Y27632 induced an invasive phenotype in low invasive lung adenocarcinoma cell lines." (PMID 28388691, 2017). "In addition, MYL9 was differentially expressed in many cancer types such as stomach adenocarcinoma, prostate adenocarcinoma, invasive carcinoma, liver hepatocellular carcinoma, lung adenocarcinoma, and squamous cell carcinoma." (PMID 37926835, 2023). "DDX17 can bind the mRNAs of MYL9 and MAGEA6 to promote the expression of MYL9 and MAGEA6, regulate the process of cytoskeletal reorganization and autophagy in lung cancer cells, thus promoting the proliferation, migration, invasion and tumor growth of lung adenocarcinoma cells." (PMID 41322492, 2025).
lung cancer (5 papers, 2017 to 2025). A malignant neoplasm involving the lung. "High MYL9 expression is associated with lymphatic metastasis in non–small cell lung cancer." (PMID 28388691, 2017). "MYL9 is the gene encoding myosin light chain 9, which is regulated by DDX17 in lung cancer and mediates the regulation of actin cytoskeletal rearrangement and cellular adhesion." (PMID 41322492, 2025). "in their study showed that the low expression of both the MYL9 and MYLK were associated with non‐small cell lung cancer (NSCLC)." (PMID 38872418, 2024). "On the other hand, high MYL9 expression was significantly associated with late tumor-node-metastasis (TNM) stage and lymphatic metastasis in non–small cell lung cancer." (PMID 28388691, 2017). "A study of MYL9 in nonsmall cell lung cancer (NSCLC) showed that the expression levels of and MYL9 were significantly lower in cancer tissue than those in the paraneoplastic and normal tissues, suggesting that low MYLK and MYL9 expressions might be associated with the development of NSCLC." (PMID 34729929, 2022).
COVID-19 (4 papers, 2022 to 2025). A disease caused by infection with severe acute respiratory syndrome coronavirus 2. "Prolonged elevation of serum Myl9 levels in patients with COVID-19 is associated with respiratory symptoms at 6 months after infection and is strongly correlated with neutrophil counts." (PMID 39879907, 2025). "Notably, elevated Myl9 levels after COVID-19 are associated with respiratory symptoms, and the blood neutrophil count is correlated with increased Myl9 levels even 6 months after infection." (PMID 39879907, 2025). "In this prospective cohort study, serum Myl9 concentrations were measured in 195 COVID-19 patients during hospitalization and at 3- and 6-month follow-up visits." (PMID 39879907, 2025). "Myosin light chain 9 (Myl9), produced by activated platelets, plays a role in immune dysregulation and microthrombi formation during acute COVID-19." (PMID 39879907, 2025). "In the acute phase of COVID-19, a correlation between Myl9 levels and neutrophil counts was previously reported." (PMID 39879907, 2025). "•Patients who have had COVID-19 can be divided into two groups according to their serum Myl9 levels." (PMID 39879907, 2025). "The median value of Myl9 in this cohort was approximately 170–200 ng/mL, which is greater than 39.4 ng/mL, the cutoff value determined by comparing healthy controls and acute COVID-19 patients." (PMID 39879907, 2025). "Furthermore, the authors found that patients can be divided into two groups according to their Myl9 levels after contracting COVID-19." (PMID 39879907, 2025). "In this study, the authors measured the serum Myl9 value during and after COVID-19." (PMID 39879907, 2025). "Comprising platelet activation, coagulation and wound healing GO terms and platelet-associated genes such as MYL9, ITGB3, GP1BB, TBXA2R and GP6, expression of the Magenta module increased modestly over time and was consistently higher in patients with severe COVID-19." (PMID 37365222, 2023). "Indeed, we have recently reported that plasma Myl9 levels were elevated and correlated with disease severity and outcome in COVID-19 patients." (PMID 36685558, 2022). "We found that plasma Myl9 levels in COVID-19 patients were similar to those in KD patients." (PMID 36685558, 2022).
gastric cancer (3 papers, 2021 to 2022). A primary or metastatic malignant neoplasm involving the stomach. "Among them, our experimental pieces of evidence demonstrated that MYL9 deficiency reduced proliferation as well as enhanced apoptosis in gastric carcinoma cells, confirming the tumorigenic function of MYL9." (PMID 35178409, 2021). "Proliferation and apoptosis were investigated in two gastric cancer cells under MYL9 deficiency." (PMID 35178409, 2021). "Among them, MYL9 deficiency reduced proliferation and enhanced apoptosis in gastric cancer cells." (PMID 35178409, 2021). "We further found that the expression level of MYL9 related to each N stage, corresponding to the degree of lymph node metastasis in gastric cancer patients." (PMID 34729929, 2022). "As for the relationship between MYL9 and PPS in gastric cancer, HR in Stage N was the highest, indicating that MYL9 expression may affect the prognosis of gastric cancer patients by affecting lymph node metastasis." (PMID 34729929, 2022). "Among aging molecular phenotype-relevant key genes, only the role of MYL9 in gastric cancer remains unknown." (PMID 35178409, 2021). "We further used the Kaplan–Meier plotter tool to study the relationship between MYL9 expression and different clinicopathological factors in gastric and ovarian cancer, finding that MYL9 expression may affect the prognosis of gastric cancer patients by affecting lymph node metastasis." (PMID 34729929, 2022). "We found that the expression level of MYL9 correlated markedly with OS and PPS, and with sex, TNM stage, Lauren classification, and HER2 status in gastric cancer except for mixed Lauren classification." (PMID 34729929, 2022).
hepatoma (3 papers, 2017 to 2023). "For instance, low expression of MYL9 was detected in clinical hepatocellular carcinoma specimens, which improved the migration and invasion of hepatocellular carcinoma cells." (PMID 37251946, 2023). "The inhibition of MYL9 phosphorylation has been shown to be beneficial in suppressing invasion in ovarian cancer and hepatoma." (PMID 34821071, 2022).
lymph node metastasis (3 papers, 2017 to 2022). "Clinical and pathological analyses showed that MYL9 expression positively correlated with advanced TNM stage, local invasion, lymph node metastasis, and poor prognosis." (PMID 36589754, 2022). "We further examined the prognostic value of MYL9 expression in tumor cells in different subgroups of patients with ESCC stratified according to tumor differentiation, T classification, and lymph node metastasis." (PMID 28388691, 2017). "OS was significantly shorter in patients with high MYL9 expression in the moderate/well tumor differentiation subgroup (n = 99, p = 0.002), T3+T4 subgroup (n = 103, p = 0.001), and in patients without lymph node metastasis (n = 67, p = 0.009)." (PMID 28388691, 2017).
non-small cell lung carcinoma (3 papers, 2021 to 2025). A group of at least three distinct histological types of lung cancer, including non-small cell squamous cell carcinoma, adenocarcinoma, and large cell carcinoma. "The tumor suppressor function of the myosin light chain 9 (MYL9) protein was recently functionally validated in non-small-cell lung cancer." (PMID 41439026, 2025). "MYL9 was previously found to be over-expressed in stages III and IV of non-small-cell lung cancer." (PMID 34771544, 2021).
ovarian carcinoma (3 papers, 2017 to 2022). A malignant neoplasm originating from the surface ovarian epithelium. "In previous results, we found that the low‐expression level of MYL9 was linked to the great prognosis of gastric and ovarian cancer patients in the Kaplan–Meier plotter dataset." (PMID 34729929, 2022). "In particular, as for the relationship between MYL9 and OS in ovarian cancer, histology exhibited the highest HR, and for the relationship between MYL9 and PFS in ovarian cancer, Stage I showed the highest HR." (PMID 34729929, 2022). "We found that the expression of MYL9 related markedly to OS and PFS and to stage and histology in ovarian cancer." (PMID 34729929, 2022).
Sepsis (3 papers, 2020 to 2023). Sepsis is defined as life-threatening organ dysfunction caused by a dysregulated host response to infection. "We have previously identified CMTM5 and ITGB3 as associates of the hub entity MYL9; key differentiators of Sepsis and SIRS with platelet activation function." (PMID 38332914, 2023). "All of these are associated with MYL9 in pediatric sepsis and in pediatric septic shock, except for CMTM5 in the latter." (PMID 32318053, 2020). "There are few shared hub-associated entities between adult and pediatric Sepsis, with the exception of GPR84-associated EXOSC4 and ENTPD7, CD177-associated DDAH2 and MYL9-associated TGFB1l1." (PMID 32318053, 2020). "The interaction maps for the sepsis group show a similar pattern to those for SIRS, i.e., specific changes in the complement of genes associated with each hub gene and significantly increased stimulatory interactions for KLRK1, FGF13, and MYL9." (PMID 32318053, 2020). "Indeed, high expression of MYL9/12 was related to sepsis-induced acute kidney injury, inflamed mouse airways, and patients with eosinophilic chronic rhinosinusitis." (PMID 32116744, 2020). "Gene entities shared between sepsis and severe sepsis response hubs are; TDRD9 – LIN7A, GPR84 – ENTPD7, PYCT1A and ZDHHC19, CD177 – DDAH2 and RGL4, SLC16A3 – DENND3 and MBD6, MYL9 – CMTM5, ITGB3, ITGA2B, NRGN, SELP and TREML1." (PMID 32318053, 2020). "The MYL9-centered hub shares entities TREML1 with adult healthy controls and TGFB1l1 with adult sepsis." (PMID 32318053, 2020). "The pattern is similar to that for pediatric sepsis with connections between nearly all hubs with the exception of KLRK1, SLC16A3, and MYL9." (PMID 32318053, 2020). "Amongst the clusters in the maps, cluster MYL9, GPR84, and SLC16A3 showed uni- and/or bi-stimulatory signals in most groups, with the exception of adult sepsis which exhibited inhibitory signals." (PMID 32318053, 2020).
vasculitis (3 papers, 2022 to 2025). "Alternatively, higher Myl9 in PACS patients would imply that vasculitis is involved in the occurrence of PACS." (PMID 39879907, 2025). "We used the LCWE-induced murine model of KD vasculitis to assess Myl9 expression in cardiovascular lesions." (PMID 36685558, 2022). "Myl9 expression was determined in coronary arteries from Lactobacillus casei cell wall extract (LCWE)-injected mice that develop experimental KD vasculitis, as well as in cardiac tissues obtained at autopsy from KD patients." (PMID 36685558, 2022). "Furthermore, in the LCWE-induced KD vasculitis mouse model, the expression of Myl9/12 was observed before inflammatory cells infiltrations." (PMID 36685558, 2022). "Further studies are needed to evaluate whether Myl9 indeed plays an important role in the pathogenesis of KD and it can be a therapeutic target of KD vasculitis." (PMID 36685558, 2022). "Furthermore, using the Lactobacillus casei cell wall extract (LCWE) murine model of KD vasculitis, we show that the expression of Myl9 is significantly increased in LCWE-induced cardiovascular lesions." (PMID 36685558, 2022). "Thus, our studies show that Myl9 expression is significantly increased during KD vasculitis and that Myl9 levels may be a useful biomarker to estimate inflammation and IVIG responsiveness to KD." (PMID 36685558, 2022). "Plasma Myl9 levels may potentially also be used as a biomarker for other types of vasculitis." (PMID 36685558, 2022). "Since activated platelets release Myl9, it has been suggested that the CD69-Myl9 system is involved in various inflammatory diseases, including vasculitis." (PMID 36685558, 2022). "Myosin light chain 9 (Myl9) is known to regulate cellular contractility of both non-muscle and smooth muscle cells, and can be released from platelets, whereas any relations of Myl9 expression to KD vasculitis have not been examined." (PMID 36685558, 2022). "Thus, the expression of Myl9/12 was detected on day 3 post-LCWE injection, when inflammatory cell infiltrations were not yet observed by HE staining and severe vasculitis was not yet induced." (PMID 36685558, 2022).
adrenal cortical carcinoma (2 papers, 2022 to 2023). "We found that high MYL9 expression in adrenocortical carcinoma, brain lower-grade glioma, and mesothelioma was associated with poor OS." (PMID 37926835, 2023). "In the analysis of clinicopathological characteristics, MYL9 expression was closely related to the tumor TNM stage in bladder urothelial carcinoma, adrenocortical carcinoma, stomach adenocarcinoma, and thyroid carcinoma." (PMID 37926835, 2023). "High expression of MYL9 in ovarian serous cystadenocarcinoma indicated worse DFS; MYL9 in adrenal cortical carcinoma, prostate adenocarcinoma, and kidney renal clear cell carcinoma showed high DSS expression, and RFS was worse." (PMID 37926835, 2023).
aneurysm (2 papers, 2022 to 2024). Bulging or ballooning in an area of an artery secondary to arterial wall weakening. "Comparing smooth muscle cell markers such as Acta2, Tagln, Myl9, Myl6, Cnn1, and Myh11, these markers were expressed less in thoracic aneurysm SMCs, suggesting a less-differentiated state of the thoracic aneurysm SMCs." (PMID 39590192, 2024).
Hepatic fibrosis (2 papers, 2016 to 2023). The presence of excessive fibrous connective tissue in the liver. "Although PAK proteins and YAP-1 have been detected in HSCs25, 26, PAK, YAP-1 and MYL9 have not previously been reported in integrin beta-1 signalling or collectively as regulators of HSC function/liver fibrosis and therefore we set about investigating these factors in greater detail." (PMID 27535340, 2016).
Megacystis (2 papers, 2020 to 2024). Dilatation of the bladder postnatally. "Megacystis-Microcolon-Intestinal Hypoperistalsis Syndrome has five types caused by MYLK, MYH11, LMOD1, MYL9, and ACTG2 genes and has unknown prevalence." (PMID 39480826, 2024).
megacystis-microcolon-intestinal hypoperistalsis syndrome (2 papers, 2020). "Global deletion of SM RLC can cause postnatal lethality in mice, with a similar phenotype as megacystis-microcolon-intestinal hypoperistalsis syndrome (MMIHS) patients who have homologous MYL9 mutations." (PMID 33424621, 2020).
mesothelioma (2 papers, 2022 to 2023). A usually malignant and aggressive neoplasm of the mesothelium which is often associated with exposure to asbestos. "The heatmap and Kaplan–Meier plot of OS in different tumors were displayed, and results showed that the low MYL9 group had a longer OS than the high MYL9 group in COAD, LGG, and MESO (mesothelioma) patients; however, the results were adverse in ACC patients." (PMID 34729929, 2022).
Mydriasis (2 papers, 2019 to 2020). Abnormal dilatation of the iris. "Importantly, our proband had congenital bilateral mydriasis, an immediately evident symptom that was also present in the other individual with MYL9‐associated MMIHS." (PMID 33031641, 2020).
pancreatic ductal adenocarcinoma (2 papers, 2022 to 2024). An infiltrating adenocarcinoma that arises from the epithelial cells of the pancreas. "The expression of MYL9 was investigated to evaluate its functional role and contribution to proliferation and apoptosis in pancreatic ductal adenocarcinoma cells in vitro." (PMID 34821071, 2022). "The results showed that MYL9 was predominantly expressed in the cytoplasm and membrane of pancreatic ductal adenocarcinoma cells." (PMID 34821071, 2022). "To investigate the expression pattern and clinical significance of MYL9 in pancreatic ductal adenocarcinoma, we performed immunohistochemical analysis of samples collected from 101 patients with pancreatic ductal adenocarcinoma." (PMID 34821071, 2022). "Our findings suggest that MYL9 is an independent prognostic factor of pancreatic ductal adenocarcinoma." (PMID 34821071, 2022). "MYL9 is a crucial biomarker and potential therapeutic target for pancreatic ductal adenocarcinoma." (PMID 34821071, 2022). "However, whole-human-genome expression arrays revealed increased MYL9 expression in pancreatic tissue in comparison with normal expression, indicating better disease- and metastasis-free survival and OS rates and demonstrating MYL9 as a novel biomarker for pancreatic ductal adenocarcinoma (PDAC)." (PMID 39768172, 2024).
rectal cancer (2 papers, 2021 to 2023). A primary or metastatic malignant neoplasm that affects the rectum. "The results showed that MYL9 expression levels significantly correlated with the most significant marker genes of various immune cells in colon and rectal cancers, including M2 macrophages, tumor-associated macrophages (TAMs), and dendritic cells." (PMID 37926835, 2023). "TIMER and GEPIA databases were used to investigate the relationship between MYL9 expression and various immune cell marker genes in colon and rectal cancers." (PMID 37926835, 2023). "The results showed that MYL9 mRNA expression was lower in colon and rectal cancers than in normal tissues." (PMID 37926835, 2023).
stomach adenocarcinoma (2 papers, 2022 to 2023). "The results showed that MYL9 expression was closely associated with TMB and MSI in stomach adenocarcinoma, skin cutaneous melanoma, and lung squamous cell carcinoma." (PMID 37926835, 2023).
thyroid carcinoma (2 papers, 2022 to 2023). "We also used the "pathological staging map" module of GEPIA2 to observe the correlation between MYL9 expression and tumor pathological staging, including COAD, KIRC (kidney renal clear cell carcinoma), THCA (thyroid carcinoma), BLCA, TGCT, OV, STAD." (PMID 34729929, 2022).
adenovirus infection (1 paper, 2022). "The plasma Myl9 levels of KD patients are much higher than those in other febrile illnesses, such as Epstein-Barr virus infection, adenovirus infection, cervical lymphadenitis, and Yersinia enteritis, the clinical features of which are similar to and often challenging to differentiate from KD." (PMID 36685558, 2022).
ADNP syndrome (1 paper, 2020). "Together with the current findings, MYL9 may play a significant role in skeletal as well as smooth muscle regulation in the ADNP syndrome." (PMID 32937737, 2020). "In this respect, MYL2 is linked to cardiac development and function, while MYL9 is involved in smooth muscle and non-muscle cell contractile activity e.g., in the gut and urinary tract, with ADNP syndrome children suffering cardiac as well as gastrointestinal problems." (PMID 32937737, 2020).
atherosclerosis (1 paper, 2022). A disease characterized by the build-up of fatty material and calcium deposition in the arterial wall resulting in partial or complete occlusion of the arterial lumen. "Upregulated genes in BBA-derived VSMCs are related to arterial mineralization and atherosclerosis, such as PTX3, SPP1, LOX, etc., whereas vasodilation and physiological regulatory genes such as MGP, ACTA2, and MYL9 were conversely enriched in conventional IA-derived VSMCs." (PMID 35874788, 2022).
Berdon's syndrome (1 paper, 2021). "The mutation of the following genes: MYH11, MYLK, LMOD1, and MYL9, is also involved in the pathogenesis of Berdon's syndrome in individual cases." (PMID 33859849, 2021).